CD44 (CD44 molecule (IN blood group))
Diseases named in the same sentence as CD44 in open-access papers (continued):
Sharing a sentence is not in itself a finding about the gene and the disease.
prostate carcinoma (continued). "Accumulating evidence has demonstrated the existence of prostate cancer stem cells, which can be been enriched by sorting for CD44+/CD133+ expression or by selecting cells that have the capacity to exclude Hoechst dye or form spheres in serum-free suspension culture." (PMID 23383988, 2013). "CD44 has been suggested to play a role in the metastatic spread of prostate cancer cells." (PMID 23476138, 2013). "We isolated CD44+CD24− stem-like cancer cells from the androgen-independent prostate cancer cell line DU145 derived from a brain metastasis of human PCa, showed their CSC properties, and investigated their phenotype and behavior with respect to the bulk DU145 cells." (PMID 22328933, 2012). "CD44 signaling increases the metastatic potential of prostate cancer cells." (PMID 22966907, 2012). "Furthermore, NF-κB and ALDH activities as well as CD44+ cells have all been highlighted as markers of prostate cancer cell migration." (PMID 22215106, 2012). "Whereas prostate cancer cell lines have less than a 2% progenitor population when cultured under long-term monolayer culture conditions, prostate cancer progenitor populations expressing CD44 and CD133 cell surface markers can be significantly enriched when grown under sphere-forming conditions." (PMID 22359577, 2012). "CD44 knockdown inhibited prostate cancer regeneration and metastasis." (PMID 22895640, 2012). "It was reported that CD44 is involved in drug resistance and metastasis in prostate cancer." (PMID 22895640, 2012). "In addition, ALDH+ cells showed an increased expression of putative prostate cancer stem cell markers (CD44 and integrin α2β1)." (PMID 21779382, 2011). "Moreover, we were able to demonstrate that surface vimentin is co-expressed on the surface of three different metastasis-derived prostate cancer cell lines with CD44 and CD133 molecules." (PMID 24212937, 2011). "Gene-expression profiling of DU145 prostate cancer cells stimulated with HGF revealed induction of a molecular signature associated with stem cells, characterized by up-regulation of CD49b, CD49f, CD44 and SOX9, and down-regulation of CD24 (‘stem-like signature’)." (PMID 22110593, 2011). "In addition, CD44+/CD24− cells isolated from prostate cancer cell lines demonstrate high tumour-forming potential in vivo." (PMID 22110593, 2011). "In a previous report, stem-like cells isolated from prostate cancer patient tumors were shown to express both CD44 and CD133 and this population had the highest colony forming capacity and could differentiate into multiple cell types." (PMID 24212937, 2011). "In prostate cancer, miR-34a inhibits cancer stem cells and metastasis by directly repressing CD44." (PMID 21923954, 2011). "In addition, flow cytometric analysis revealed that vimentin expression was readily detected along with CD44 expression but only a small subpopulation of prostate cancer cells expressed vimentin and the putative stem cell marker CD133 along with CD44." (PMID 24212937, 2011). "CD44, a cell-surface molecule proposed to identify cancer stem/progenitor cells in prostate cancer, has been demonstrated to be highly specific of small cell carcinoma of the prostate, when compared to conventional acinar adenocarcinoma or small cell carcinomas of other sites." (PMID 22110988, 2011). "Dysregulated CD44 expression characterizes most human cancers, including prostate cancer (PCa)." (PMID 20074368, 2010). "Due to the existence of wide variation in the pathways leading to Erk1/2 activation, we investigated the OPN induced signaling pathway(s) which lead to Erk1/2 activation in prostate cancer cells and the role of cell surface receptors (αvβ3 and CD44) in this process." (PMID 20868520, 2010). "Taken together, this evidence supports the hypothesis that CD44+CD24− cells are the tumour-initiating cells in the prostate cancer cell lines." (PMID 18268494, 2008). "The CD44+CD24− prostate cancer cells are highly clonogenic and tumorigenic cells." (PMID 18268494, 2008).
prostate carcinoma (continued). "CD44/MMP-9 complex formation on the cell surface may represent a unique motility-enhancing signal in prostate cancer cells, thereby promoting their invasiveness." (PMID 17343740, 2007). "Also, CD44 expression on prostate cancer cells (PC3) derived from bone metastases has been shown to have a role in their selective adhesion to bone marrow endothelium." (PMID 17343740, 2007). "There are also numerous publications reporting mRNAs containing retained intronic sequences, including the retention of CD44 introns in bladder cancer, and the recently-described upregulation of the novel proapoptotic BH3-only splice variant of BIM in prostate cancer cells." (PMID 15162151, 2004). "Moreover, in prostate cancer, miR-34a is markedly underexpressed in cancer stem cell (CD44+) subpopulations; enforced re-expression of miR-34a significantly inhibits tumor regeneration and metastasis, likely through targeting of stemness and survival regulators such as CD44, NOTCH, MYC, and BCL-2." (PMID 41465187, 2025). "Thus, a 5′-CpG island of CD44 is methylated in prostate cancer." (PMID 38247821, 2024). "In addition, the combination of CDC20 and CD44 or β-catenin could be used as an important indicator of the prognosis of prostate cancer patients." (PMID 35800227, 2022). "ALDH+ CD44+ prostate CSCs showed increased expression of B7-H3 after radiotherapy, and the expression difference between CSCs and bulk prostate cancer cells indicates that B7-H3 targeting immunotherapy is a promising combination alternative for prostate cancer therapy." (PMID 36284349, 2022). "However, the underlying molecular mechanisms by which CD44-ICD regulates prostate cancer metastasis has not been studied." (PMID 31331331, 2019). "Many potential stem cells markers have been identified in prostate, however the CD44+/CD24− cells have been associated with the prostate cancer stem cells which possess the ability to grow as nonadherent spheres in serum replacement medium and a potential to form tumors in NOD/SCID mice." (PMID 28758908, 2017). "Therefore, using miR-708-5p as a therapeutic in prostate cancer may be more efficacious than other CD44 targeting agents." (PMID 29050362, 2017). "In addition, CD44+ stem-like cell population increases in prostate cancer cells following ADT–induced TGF-β signaling activation leading to de-differentiated phenotype of prostate cancer cells." (PMID 28430640, 2017). "Interestingly, the CD44+α2β1hiCD133+ prostate cancer cells have been shown to be PCSCs." (PMID 28400729, 2017). "CD44 is recognized as the principal receptor for hyaluronic acid (HA) and CD44-HA interactions have been demonstrated to affect many physiological and disease processes including promoting keratinocyte activity, improving abnormal epidermal function and melanoma and prostate cancer development." (PMID 27505250, 2016). "It has been reported that hypermethylation of the CpG islands located in the promoter region of the stem/precursor cell marker CD44, one of the colorectal and other cancer stem cell surface markers, might predict biochemical recurrence in prostate cancer patients undergoing radical prostatectomy." (PMID 26599100, 2015). "Hellsten and colleagues find that ALDH + prostate cancer cells are cancer stem cell-like cells as they display the properties of CSCs such as self-renew, clonogenicity and tumorigenicity as well as elevated expression of CD44 and integrin α2β1, two CSCs markers, and pSTAT3." (PMID 24618337, 2014). "However, little is known regarding whether cells with the CD133+/CD44+ phenotype are prostate cancer stem-like cells (PCSLCs)." (PMID 23426586, 2013). "In addition, our previous work showed that the PI3K/AKT/FOXO3A axis is a critical regulator of CD44+/CD133+ progenitor populations within prostate cancer cells, and that FOXO3a-dependent gene expression is inhibited in CD44+/CD133+ prostate cancer progenitors versus CD44+/CD133+ cell population." (PMID 22359577, 2012).
prostate carcinoma (continued). "The mechanism by which CD44 regulates the progression of prostate cancer is largely unknown." (PMID 22966907, 2012). "γ-tocotrienol is also an effective agent in targeting prostate cancer stem cells through the down-regulation of stemness markers (CD133, CD44), the elimination of chemoresistance, and decreased viability (both in vitro and in vivo)." (PMID 39859345, 2025). "Cell cycle arrest and inhibition of the survival, proliferation, and migration of PC3 cells expressing CD44 and CD133 isolated from prostate cancer by inhibiting p‐p38, p‐ERK, NF‐κB, and PARP." (PMID 38783892, 2024). "Studies used different human prostate cancer cell lines including PC-3, DU145, LNCaP, CD44+/CD133+ HuPCaSCs, C4-2, and 22RV1." (PMID 39445208, 2024). "Pretreated and posttreated prostate cancer cell lines were stained with stemness markers CD44, CD133, and both CD44/133 antibodies." (PMID 37476073, 2023). "In prostate cancer, surviving cells after high-dose radiation have an enhanced sphere-forming capacity and high expression of the CSC marker CD44, and this stemness profile is progressively enhanced within one week after irradiation." (PMID 37213675, 2023). "In the AA prostate cancer subtype (MDA-PCa-2b and RC77T/E), “stem-like” CD44+ cell proportions were 16.6% and 5.69%, respectively." (PMID 37476073, 2023). "In a prostate cancer model investigating αvβ3–OPN blockade, bisphosphonates were found to inhibit the subsequent Rho GTPase activation, thus attenuating CD44/MMP-9 binding and reducing prostate cancer cell migration." (PMID 37239027, 2023). "CD44 also promotes epithelial-mesenchymal transition (EMT) in many cancer types such as colon cancer, gastric cancer, pancreatic cancer, prostate cancer, liver cancer, and glioma by upregulating mesenchymal markers and downregulating epithelial markers." (PMID 37593530, 2023). "The regulatory functions of NOS-NO signaling were evaluated in prostate cancer cells, especially in PCSCs enriched by 3D spheroid culture and CD133/CD44 cell sorting." (PMID 35526071, 2022). "The coexpression of CD44 and CD133 has been shown to be related to worse clinical outcomes and the survival of cancer patients, including those diagnosed with prostate cancer." (PMID 35912174, 2022). "Several studies have reported that CD44+/CD24− cells have CSC properties in breast and prostate cancers." (PMID 36498950, 2022). "CD133 and CD44 cell surface markers are putative CSC markers for different tumors, including prostate cancer." (PMID 35912174, 2022). "Expression of CD44 contributes to the enhanced bone metastasis in the human prostate cancer cell line PC3, grade IV prostate cancer, by promoting tumorigenicity, cell invasion, migration and HA production." (PMID 34944493, 2021). "The authors examined the effect of quercetin on CD44+/CD133+ and CD44+ stem cells isolated from prostate cancer cells (PC3 and LNCaP cells, respectively)." (PMID 34884848, 2021). "Among them, the change in CD44 and CD133 expression, which are used widely to separate and characterize prostate cancer stem cells, were examined." (PMID 34745437, 2021). "A non-malignant cell line RWPE-1 as well as prostate cancers PC-3 and DU145 demonstrated the CD44+/CD24- and CD44+/CD24+ phenotypes of progenitor cells, while prostate cancers 22Rv1 and LNCaP demonstrated CD44-/CD24- and CD44-/CD24+ phenotypes." (PMID 34019593, 2021). "This study aimed to determine the biological consequence of CD44 cleavage and its potential interaction with Runt-related transcription factor (RUNX2) in a sequence-specific manner in PC3 prostate cancer cells." (PMID 33062960, 2020). "In prostate cancer, CD44 expression significantly correlates with IL-6, a STAT3-activating cytokine, and IL-6 or STAT3 inhibition both decrease CD44 and EMT-related protein levels in cancer cell lines." (PMID 33335857, 2020).
prostate carcinoma (continued). "We first reconfirmed the expression levels of CD44, CD44-ICD, and RUNX2 in three significant prostate cancer cell lines (LNCaP, PC3, and PCa2b)." (PMID 33062960, 2020). "In laryngeal and prostate cancer models, expression of hg19_circ_0005033 in CD133+/CD44+ CSCs has been allied with EMT promotion and the subsequent increase in CSC migratory and invasive capabilities, via Jak2/STAT5A signaling upregulation." (PMID 32932969, 2020). "When blocking IL-6 using antibody or STAT3 inhibition, the expression levels of CD44 and EMT-related proteins in prostate cancer cells were significantly attenuated both in vitro and in vivo." (PMID 31315262, 2019). "Accordingly, we further identified a role for IL-6 in CD44 expression, CSC-like properties, and the TME in prostate cancer." (PMID 31315262, 2019). "Similar to miR-34a, miR-141 was underexpressed in CD44+ prostate CSCs, inhibited tumor regeneration when expressed in prostate cancer cell lines, and regulated CD44 through a putative miR-141 binding site in the 3’UTR of CD44." (PMID 30860027, 2019). "The interaction of CD44, a cell surface adhesion receptor, and matrix metalloproteinase 9 (MMP9) results in secretion of active MMP9 leading to migration and invasion of prostate cancer cells." (PMID 31358880, 2019). "The CD44-positivity of the cells grown in 3D MCS was determined by immunocytochemistry and was elevated in bladder cancer, prostate cancer, and glioma cell lines compared with 1 g-cultures." (PMID 31731625, 2019). "CD44, a cell surface receptor for hyaluronic acid (HA), osteopontin (OPN) and many other ligands has been shown to play a key role in prostate cancer (PCa) metastasis, migration, and invasion." (PMID 31331331, 2019). "In the prostate cancer cell line PC3, an isoform of CD44 with the molecular weight of 85–90 kDa was predominantly precipitated by mAb F77." (PMID 29423071, 2018). "For example, some membrane markers, including CD44, CD133, CD24, and α2β1 integrin, are used successfully by these methods to isolate prostate cancer stem-like cells (PCSCs) or tumor progenitor cells from cell lines and primary tumors." (PMID 30257704, 2018). "In a study investigating the differences in glucose metabolism between two forms of prostate cancer, small cell neuroendocrine carcinoma (SCNC) was found to be more glycolytic than adenocarcinoma, CD44 being a key regulator of glucose metabolism." (PMID 30234009, 2018). "The impact of IL‐6 on CSCs on other prostate cancer cell lines in our panel was measured by FACS, where the fraction of CSCs was measured based on triple‐marker‐positive status (CD44+/CD133+/EpCAM+)." (PMID 29741809, 2018). "One hundred forty-eight prostate tissues composed of prostate cancer (PCa), high-grade prostatic intraepithelial neoplasia (HGPIN), and benign prostate hyperplasia (BPH) were immunostained for CD44 and CD133." (PMID 29747682, 2018). "The interaction of CD44 and proteolytic form of MMP-9 is particularly involved in the invasion of prostate cancer cells (PC3) derived from bone metastases." (PMID 28326306, 2017). "We enriched and purified CSCs (CD44+/high/CD24−/low or CD133+ population) from breast and prostate cancer cell lines, and demonstrated their stemness phenotype." (PMID 28569785, 2017). "Using flow cytometry we identified CD44+/CD24− subpopulation in PC3 and DU145 human prostate cancer cell lines." (PMID 28758908, 2017). "Prostate cancer stem cells were characterized by the expression of several markers such as CD24, CD44, CD49f, CD133, CD166, and α2β1 integrins." (PMID 28758908, 2017). "CD44+ cancer stem/progenitor cells, in response to TGF-β signaling, not only can initiate the EMT but also can regulate the mesenchymal phenotype in prostate cancer cells." (PMID 28430640, 2017). "Nanog was found to be upregulated, which enhanced the expression of typical cancer stem cell markers, such as CD44, CD133, and ALDH1A1 in prostate cancer." (PMID 27829864, 2016).
prostate carcinoma (continued). "On the other hand, CD44 was found in 97% of benign prostate and HGPIN cases, and in 72% of prostate cancer cases." (PMID 27447616, 2016). "DU145 and PC-3 human prostate cancer cells were sorted for CD133 and CD44 surface expression with FACS." (PMID 26485709, 2015). "The reason no distinct difference was apparent between the CD44 serum level in healthy subjects and tumor patients may have been because CD44 variants such as CD44v5, CD44v6 and CD44v10, possibly involved in prostate cancer progression, were not individually evaluated." (PMID 25967040, 2015). "A similar profile of increased expression and activation of the α5 and β1-integrin receptors was also detected in CD44-positive PC3 cells, a bone-metastatic prostate cancer line, in response to HA." (PMID 26447611, 2015). "Prostate cancer stem cells isolated from LNCaP and DU145 cell lines also showed expression of CD44(+), α2β1high, and CD133(+) markers." (PMID 23936768, 2013). "Analogous to TMPRSS2/ERG in prostate cancer, the SLC1A2 fusion in gastric cancer is thought to be driven by strong expression of its 5′ partner, CD44." (PMID 23637631, 2013). "We also showed that salinomycin had an impact on prostate cancer stem cell population using ALDH activity and the amount of CD44+ cells as markers." (PMID 22215106, 2012). "At first, we evaluated the expression levels of CD44 in control cells (HPR1 and BPH) and prostate cancer cells derived from bone (PC3), lymph node (LNCaP) and brain (DU145) metastases." (PMID 22966907, 2012). "Activation of the CXCR4/CXCL12 signaling pathway significantly increases the CD44+/CD133+ population for both PC3 and DU145 prostate cancer cell lines in a dose dependent manner (up to 3.5-fold and 2.6-fold increase, respectively)." (PMID 22359577, 2012). "In prostate cancer cells (PCas), CD44+ PCa cells are more proliferative, clonogenic, tumorigenic, and metastatic than the isogenic CD44− PCa cells." (PMID 22634835, 2012). "Prostate cancer cells expressing CD44 and CD133 cell surface markers can be enriched from prostate cancer cell lines by growing them as spheres in progenitor media conditions." (PMID 22359577, 2012). "We show here that phosphorylation of Smad 5 by integrin αvβ3 and RUNX2 by CD44 signaling, respectively, regulates RANKL expression in human-derived PC3 prostate cancer cells isolated from bone metastasis." (PMID 22966907, 2012). "We found that treatment of the prostate cancer cell line PC-3 with PSP led to the down-regulation of CSC markers (CD133 and CD44) in a time and dose-dependent manner." (PMID 21603625, 2011). "Surface vimentin was found to be co-expressed on a subpopulation of cells along with CD44 and CD133 suggested to be markers of prostate cancer stem cells." (PMID 24212937, 2011). "Further, c-MET activation led to a 3.25-fold enrichment of CD44+/CD24− cells, representing more accurately the stem-like cell profile for breast and potentially prostate cancer." (PMID 22110593, 2011). "Treatment of prostate cancer cell line PC-3 with PSP led to the down-regulation of CSC markers (CD133 and CD44) in a time and dose-dependent manner." (PMID 21603625, 2011). "Almost all known transcription targets activated by the Wnt/β-catenin pathway, e.g. CTNNB1, CCCNDs, MMPs, PITX2, CD44, APCDD1, JUN, remain unchanged or are down-regulated in prostate cancer tissue or cell lines compared to normal tissue or cell line." (PMID 20454608, 2010). "Mining of publicly available human prostate cancer oligoarray datasets revealed that the expression of numerous genes (e.g., CCND1, CD44) under the control of β-catenin transcription is down-regulated." (PMID 20454608, 2010). "In prostate cancer, a CSC population with the CD44+/integrinα2β1hi/CD133+ phenotype has been identified that exhibits extensive proliferation, self-renewal, differentiation, and invasion." (PMID 18349830, 2008).